INS (insulin)
Diseases named in the same sentence as INS in open-access papers (continued):
Sharing a sentence is not in itself a finding about the gene and the disease.
Insulin resistance (continued). "Later on, other authors demonstrated that myo-ins is even more efficient than metformin in raising sensitivity to insulin, thus lowering serum insulin levels, homeostatic model assessment of insulin resistance index (HOMA-IR), and LDL cholesterol levels." (PMID 34070701, 2021). "Our results showed significant reverse correlations between PLIN3 and insulin resistance indices (glucose, insulin, and HOMA-IR) in all groups." (PMID 34765049, 2021). "T2D is characterized by hyperglycemia, insulin resistance, and relatively impaired insulin secretion." (PMID 34603195, 2021). "Some research, particularly in animal models of insulin resistance, have shown that brain insulin signaling plays a role in neuropathology including as relevant to cerebrovascular disease, such as IRS1/AKT in hypoxic brain injury." (PMID 33858515, 2021). "Chronic hyperglycemia also impairs insulin signaling in insulin target tissues, which leads to the progression of insulin resistance." (PMID 33802741, 2021). "Elevated NEFA contribute to insulin resistance in humans through such mechanisms as downregulation of insulin-signaling, resulting in impaired peripheral glucose uptake and glycogen synthesis." (PMID 32767274, 2021). "The phenomenon of psychological insulin resistance, in which insulin refusal is based on the patient’s perceptions, fears, or assumptions of therapy (but not clinical facts), can affect physicians, as well as patients." (PMID 34712538, 2021). "This leads to an increase in the basal secretion of insulin and induces hyperinsulinemia, thus contributing to a chronic exposure of cells to insulin and to the development of insulin resistance fostered also by the concomitant low grade inflammation." (PMID 33499378, 2021). "HOMA2%B is an index of basic insulin secretion, which represents the ability of islet β-cells to compensate against insulin resistance." (PMID 33413319, 2021). "Circulating myostatin is basically increased in obese subjects; its concentration correlates positively with insulin resistance/pancreatic β-cell dysfunction indicators and negatively with insulin sensitivity indicators." (PMID 34959945, 2021). "Resulting elevation of free fatty acids signals the release of pro-inflammatory cytokines, which then activate insulin inhibition signaling and the further promotion of insulin resistance." (PMID 34943038, 2021). "A2B adenosine receptor knockout mice fed an HFD developed hallmarks of the metabolic syndrome and T2DM (such as insulin resistance and increased insulin levels and were more obese than wild-type littermates." (PMID 34943862, 2021). "The macrophages in fatty cells secrete proinflammatory cytokines such as CRP, and cytokines which impair insulin signaling, inducing insulin resistance." (PMID 34661762, 2021). "As result, compensatory insulin secretion increases, which in turn aggravates insulin resistance, potentially leading to development of GDM." (PMID 34803906, 2021). "After adjusting for covariates, the FFS pattern was positively associated with Wt, SBP, WC, insulin, and HOMA-IR, and caused a significantly higher prevalence of insulin resistance." (PMID 33807269, 2021). "This first phase of insulin secretion appears to play an important role in the diagnosis of insulin resistance." (PMID 35011145, 2021). "Previous studies, including our own, clearly indicated that proliferation rate and viability of cells is strongly affected by insulin resistance and that enhancement of insulin sensitivity is able to restore the progression of cell cycle." (PMID 34034759, 2021). "Depression-like behaviors were associated with age, body image-related factors, hyperandrogenism-related factors, and metabolic factors (including fasting insulin, fasting plasma glucose, and homeostatic model assessment of insulin resistance)." (PMID 34744814, 2021). "Fasting insulin levels, fasting glucose levels, and Homeostatic Model Assessment for Insulin Resistance (HOMA-IR) levels were evaluated." (PMID 34491995, 2021).
Insulin resistance (continued). "Some of the pathways, for instance, insulin signaling, insulin resistance or adipocytokine signaling appear among both positively and negatively associated terms." (PMID 34564389, 2021). "In the present study, we show that challenging BKO mice with an obesogenic diet resulted in increased plasma insulin levels but also in a more pronounced impairment of insulin resistance already after two weeks of HFD feeding, before the onset of obesity." (PMID 34015524, 2021). "The secondary endpoints were used to detect the glycemic profile, and the insulin resistance were the determination of glycemia and insulin levels, respectively." (PMID 34684666, 2021). "After detecting the concentration of fasting serum glucose, insulin and C-peptide, the index of the homeostasis model assessment of insulin resistance (HOMA-IR) and islet β-cell secretion (HOMA-β) were calculated." (PMID 34948750, 2021). "Three days of HFD feeding are sufficient to cause insulin resistance in the DVC and prevent an insulin-dependent decrease in food intake." (PMID 33227495, 2021). "Higher baseline cervical and chin-SAT correlated with increased WC, diastolic and systolic blood pressure, leptin, insulin, HbA1C, and homeostasis-model-assessment-of-insulin-resistance (HOMA-IR; p < 0.05 for all)." (PMID 34836081, 2021). "IL-6, up to 30% of which is produced by adipose tissue, negatively regulates insulin signalling and glucose metabolism in adipocytes, and promotes insulin resistance in liver cells." (PMID 34658643, 2021). "At 12 months there were significant reductions in BMI, waist circumference, fasting insulin, insulin resistance according to homeostatic model assessment (HOMA-IR) with a corresponding increase in the insulin sensitivity." (PMID 33449916, 2021). "One of the methods to assess insulin resistance is to assess both fasting glucose and insulin levels and calculate the Homeostatic Model Assessment for Insulin Resistance (HOMA-IR)." (PMID 34680464, 2021). "Insulin resistance is a pathological condition in which the body’s cells become resistant to the effects of insulin." (PMID 34243726, 2021). "It is characterized by poor blood glucose control due to insulin resistance and progression apoptotic death of insulin-producing islet β-cells." (PMID 34824300, 2021). "In persons with PCOS, metformin was reported to reduce IR (also known as insulin resistance) as one of the insulin sensitizers." (PMID 34745009, 2021). "Production of TNF-α by ILC1s would lead to further exacerbation of insulin resistance which has a variety of downstream consequences for insulin signaling." (PMID 34489979, 2021). "The evaluated indicators of insulin resistance included fasting glucose, fasting insulin, and homeostasis model assessment-estimated insulin resistance (HOMA-IR) collected pre- and post-intervention." (PMID 34568974, 2021). "Glutamate also affects the activation of the IR and downstream effectors, when being added prior to insulin exposure, thereby developing acute neuronal insulin resistance within minutes." (PMID 33810179, 2021). "Treatment of obese rats with PRL improves insulin sensitivity and challenging global Prlr null mice with an obesogenic diet exacerbates insulin resistance and glucose intolerance." (PMID 33746901, 2021). "A study in 74 obese children revealed that individuals with acanthosis nigricans had significantly greater fasting insulin level and homeostatic model assessment insulin resistance (HOMA-IR) score." (PMID 33562009, 2021). "In T2DM a series of metabolic dysfunctions occur such as diminished insulin action and impaired insulin secretion, elevated hepatic glucose production, and increased insulin resistance (IR)." (PMID 34284789, 2021). "Insufficient insulin secretion in T2D, and its relationship to obesity, insulin resistance, and aging, are also well documented." (PMID 34822454, 2021).
Insulin resistance (continued). "The lower Si and lower Di suggest both a reduction in insulin sensitivity and a failure of the β-cells to fully compensate for the insulin resistance." (PMID 34200102, 2021). "The ontology of these genes and pathway analysis have demonstrated insulin resistance, insulin and adipokine signaling, amino acid metabolism, and T2DM." (PMID 35046895, 2021). "In the period of insulin resistance, this hormone is ineffective, which induces an increase in insulin production." (PMID 33505497, 2021). "Dipeptidyl peptidase (DPP-4) inhibitors increase incretin hormone levels, which improve insulin secretion, insulin resistance and reduce glucagon levels, and they have been proven to be effective and safe in patients with T2D36–38." (PMID 33888772, 2021). "We demonstrated a downmodulation of the global phospholipidome in PBMCs from OBDysG compared to lean patients which is mainly associated with insulin resistance (i.e., HOMA-IR and fasting insulin)." (PMID 34684461, 2021). "Given that one of the mechanisms of PCOS pathogenesis is insulin resistance, we studied our patients’ fasting insulin levels, blood glucose levels of patients in both groups, and the HOMA index." (PMID 35126755, 2021). "Our results also underline the complexity of the interrelationship of androgen excess with weight, insulin resistance, and insulin secretion." (PMID 34153097, 2021). "Peripheral insulin resistance during pre-T2D places an immense workload on the β-cells to release an extraordinary volume of insulin." (PMID 33673206, 2021). "Insulin resistance impairs glucose processing, leading to a compensatory increase in beta cell insulin production and hyperinsulinemia." (PMID 34803916, 2021). "The combined effects of insulin resistance and abnormal insulin secretion together with other important mechanisms such as dysregulated secretion and/or action of incretin hormones and kidney glucose reabsorption lead to increased blood glucose levels." (PMID 34394004, 2021). "Insulin resistance stimulates the pancreas to increase insulin secretion from the portal vein, leading to higher levels of insulin in the liver than in the periphery." (PMID 34083664, 2021). "It has been demonstrated that insulin signaling is impaired during oxidative stress, resulting in insulin resistance of the cell." (PMID 33466692, 2021). "In mice, global ROCK1-deletion triggers whole body insulin resistance by impairing skeletal muscle insulin signaling." (PMID 34443331, 2021). "This underscores our approach to take account of HOMA-IR when evaluating HOMA-β because insulin secretion will adapt to increased demands due to insulin resistance." (PMID 34321006, 2021). "The leading genetic factors behind T2D are impaired insulin secretion or insulin resistance, or it can even be both due to impaired pancreatic β-cells." (PMID 34674647, 2021). "Excess of circulating FFAs or elevated levels of pro-inflammatory cytokines impair insulin signaling and promote the establishment of insulin resistance." (PMID 33753887, 2021). "It significantly reduced the levels of FPG concentrations and insulin resistance, and insulin sensitivity increased by the low-dose treatment of flaxseeds." (PMID 34540481, 2021). "NMR biomarkers of insulin resistance are important to explore in youth because they would facilitate estimation of an insulin independent marker of insulin resistance." (PMID 34084151, 2021). "Diabetes mellitus is a worldwide metabolic disease induced by insufficient insulin secretion or insulin resistance and featured by hyperglycemia and metabolism disorder." (PMID 34959930, 2021). "Inhibitors of DPP-4 improve neuronal insulin resistance by restoring insulin-induced phosphorylation of neuronal IR, IRS1 phosphorylation, and AKT/PKB-Ser phosphorylation, resulting in the brain mitochondrial dysfunction." (PMID 34489627, 2021).
Insulin resistance (continued). "Increased secretion of insulin can result in insulin resistance, characterized by defects in glucose metabolism, triggering oxidative stress, inflammation and cell damage." (PMID 34827683, 2021). "High-fat meals impair insulin signaling, which results in a transient increase in insulin resistance in mechanistic studies." (PMID 33806867, 2021). "Patients with T2DM usually have pathological factors of insulin resistance, it leads to impaired insulin function, insufficient insulin secretion, and long-term hyperglycemia." (PMID 33592865, 2021). "In fact, one single session of exercise is able to improve both insulin-induced glucose uptake and insulin signaling in rodents fed with high-fat diet, which is an established model of insulin resistance." (PMID 32737757, 2021). "IL-6/Jak2 signaling adversely interferes with the action of insulin, resulting in glucose intolerance and insulin resistance." (PMID 34943061, 2021). "The fact that when adjusting by leptin this favorable association of the polymorphism with insulin and HOMA emerges supports the role of PPARγ in relationship with insulin resistance already at this age." (PMID 34887761, 2021). "When T2DM occurs, the body develops insulin resistance, and the utilization rate of insulin is reduced, resulting in an increase in blood sugar that cannot be reduced." (PMID 34722505, 2021). "As expected, insulin resistance, type II diabetes mellitus, insulin signaling pathway, and adipocytokine signaling pathway were the frequently reported events and molecular processes associated with obesity." (PMID 34131148, 2021). "Those with preexisting insulin resistance had both higher fasting insulin and insulin resistance in the case of palm oil and partially hydrogenated soybean oil diets, compared with canola or soybean oil diets." (PMID 34681504, 2021). "Experimental and clinical evidence suggests that oxidative stress increases leptin secretion by adipocytes, induces β-cell dysfunction, and impairs insulin signaling and glucose tolerance, leading to the development of insulin resistance." (PMID 34017260, 2021). "It is characterized by insulin resistance, which is defined as a poor response of insulin-sensitive tissues to normal insulin concentration." (PMID 35002743, 2021). "In their study, Ying and colleagues showed that exosomes derived from adipose tissue macrophages of obese mice and injected into lean mice induce glucose intolerance, insulin resistance and increased glucose-stimulated insulin secretion." (PMID 33578952, 2021). "In fact, a recent survey revealed that LRP1 polymorphism is the top gene variation among 1,000 candidate gene variations in influencing fasting insulin and C-peptide levels and insulin resistance in patients with metabolic syndrome." (PMID 33500241, 2021). "To further explore the insulin resistance defects, we examined glucagon responses following insulin injection during the insulin tolerance tests in the two individual knockouts." (PMID 33839150, 2021). "It is well known that insulin resistance is manifested by a decrease in insulin stimulate glucose uptake in skeletal muscle." (PMID 34521490, 2021). "Inflammatory cytokines can cause structural and functional abnormalities of endothelial cells, leading to insulin transport disorders in human tissues and cells and thus lead to insulin resistance." (PMID 33553435, 2021). "Because HFD-induced obese mice develop glucose intolerance and insulin resistance, we next compared the insulin sensitivity of WT and Brd4-CKO mice fed a ND or a HFD by the glucose tolerance test (GTT) and insulin tolerance test (ITT)." (PMID 33830083, 2021). "In some T2D patients, insulin resistance predominates and in other patients, reduced insulin secretion is the main dysfunction." (PMID 33387681, 2021).
Insulin resistance (continued). "They promote insulin secretion, decrease glucagon release and improve β-cell function, influencing insulin resistance and increasing insulin sensitivity, as well delaying gastric emptying." (PMID 34830194, 2021). "It is reported that the mice knockout for SCF Fbxo40 shown elevated levels of IRS1 of the insulin signaling pathway and play a vital role in insulin resistance." (PMID 33669862, 2021). "As such, insulin levels would presumably be maintained at low levels while fasting, and if combined with any degree of peripheral insulin resistance, would contribute to sustained and elevated glucose levels." (PMID 33766933, 2021). "A large percentage of prediabetes patients showed a rise in IR index, and they labeled as insulin-resistant patients when the value of the homeostasis model assessment of the insulin resistance (HOMA2IR) reaches the cut-off value (> 2.5)." (PMID 34099024, 2021). "Obesity disrupts immune homeostasis, increases inflammatory cell infiltration, and reduces insulin sensitivity, thereby increasing insulin resistance." (PMID 34444874, 2021). "In fact, the HFS diet-induced elevation in blood insulin concentration was 79%, relative to the SC animals, which is an indication of insulin-resistance in these animals." (PMID 34684358, 2021). "Compared with the NC group, serum fasting blood glucose levels and insulin contents in the DC group were increased (p < 0.01), indicating that insulin resistance was severe in the DC group." (PMID 33794128, 2021). "This meta-analysis contains 30 articles that study the effects of RV supplementation vs. a placebo on glucose, insulin, HbA1c, and insulin resistance (measured by the HOMA-IR index)." (PMID 33430470, 2021). "In the initial stage of the disease, a decrease in insulin sensitivity known as insulin resistance is observed and, to compensate, pancreatic cells increase insulin secretion resulting in a state of hyperinsulinemia." (PMID 34366888, 2021). "We included 47 healthy adults, 46 new‐onset T2D with insulin resistance, and 51 patients with insulin therapy." (PMID 34272768, 2021). "As estrogen optimizes insulin activity, multiple studies have aimed to understand glucose metabolism and insulin resistance levels in patients with POI." (PMID 34394393, 2021). "Thiazolidinediones (TZD) are a group of drugs that exert their effects by acting on the liver, skeletal muscle, and adipose tissue where they reduce insulin resistance and improve tissue sensitivity to insulin through the activation of PPAR-γ." (PMID 35011414, 2021). "Studies have reported that S1P in the extracellular environment binds to S1PR2 on hepatocytes, which results in diminished insulin signaling and insulin resistance (IR)." (PMID 34950103, 2021). "Herein, we found that pancreatic β cells respond to high levels of FFAs by secreting exosomal miR‐29s to target the hepatic insulin signalling pathway and promote insulin resistance." (PMID 33520119, 2021). "Previous studies have shown that delayed glucose peak time was correlated to decreased insulin sensitivity, increased insulin resistance, and failure of pancreatic β-cell function in patients with diabetes." (PMID 34789863, 2021). "In these patients, increased insulin resistance, increased hepatic gluconeogenesis, impaired intracellular glucose metabolism, decreased insulin clearance and decreased insulin secretion potentiated by metabolic acidosis are observed." (PMID 34625090, 2021). "So, by limiting the peripheral use of glucose, insulin resistance determines increased levels of insulin in plasma." (PMID 34575946, 2021). "Impaired insulin secretion and insulin resistance are hallmarks of aberrant glucose disposal, and type 2 diabetes (T2DM)." (PMID 33815283, 2021). "Increases in fasting plasma glucose, insulin, and homeostasis model assessments of insulin resistance in OVX Sprague Dawley rats treated with GlcN were reversed by RLX treatment (n = 8 in each group)." (PMID 34572301, 2021).